INS (insulin)
Diseases named in the same sentence as INS in open-access papers (continued):
Sharing a sentence is not in itself a finding about the gene and the disease.
Insulin resistance (continued). "This schema, in combination with low-dose insulin therapy, would combat the cardiometabolic effects of the disease and also subsequently slow the process of acquired insulin resistance associated with T1D." (PMID 40429969, 2025). "SZ is associated with metabolic complications including high insulin and glucose, insulin-resistance, metabolic syndrome, and diabetes." (PMID 41356674, 2025). "Obesity is associated with insulin resistance and increased demand for insulin to maintain glucose homeostasis." (PMID 40134803, 2025). "Elevated IL-6 levels are commonly observed in obesity and have been linked to altered insulin sensitivity in hepatic tissue and pancreatic β-cells, thereby contributing to the development of insulin resistance." (PMID 40722699, 2025). "Insulin strongly correlated with BMI and FM, strengthening the association between fatness and insulin resistance." (PMID 41394365, 2025). "Obesity has been linked to genetic predispositions that alter insulin and leptin signaling, contributing to insulin resistance and leading to behavioral disorders, including aggression and social isolation." (PMID 40367227, 2025). "Several factors have been described as the possible reasons underlying the emergence of insulin resistance, such as an increase in visceral adiposity and genetic deformations in one or more proteins involved in the insulin mechanism of action." (PMID 40729004, 2025). "ROS cause damages to pancreatic β cells and impair insulin signaling toward reduced insulin secretion and promoted insulin resistance." (PMID 40989573, 2025). "Acromegaly predisposes to insulin resistance, and the diabetogenic effect of GH would seem to outweigh the insulin-sensitizing effect of IGF-1." (PMID 40088375, 2025). "Although it has been discovered that intermittent hypoxia causes insulin resistance, chronic hypoxia typically improves insulin action." (PMID 40283443, 2025). "Compared to controls, GoF LRP5 mutation carriers exhibited lower fasting glucose, fasting insulin, Homeostatic Model Assessment for Insulin Resistance (HOMA-IR), HOMA of β-cell function (HOMA-B), and adipose tissue insulin resistance (Adipo-IR)." (PMID 40000740, 2025). "The stress in beta cells is caused by increased insulin secretion to compensate for peripheral insulin resistance." (PMID 39859066, 2025). "Sleep deprivation can lead to insulin resistance, where cells become less responsive to insulin, causing elevated blood glucose levels." (PMID 40868130, 2025). "Insulin resistance is a primary pathogenic mechanism in T2D and a significant factor contributing to inadequate insulin secretion." (PMID 40260393, 2025). "Insulin was included as a candidate predictor based on prior studies suggesting an association between vitamin D status and insulin resistance, particularly in premenopausal women." (PMID 40431396, 2025). "A patient with MODY and obesity-driven insulin resistance, who is insulin dependent, can potentially be weaned off insulin with weight loss and reversal of the insulin resistance." (PMID 39717432, 2025). "Insulin levels, C-peptide, and markers of insulin resistance and beta-cell function were all significantly associated with higher METS-IR values in every case." (PMID 40218212, 2025). "Smoking increases the risk of T2DM by inducing insulin resistance or decreased insulin secretion through oxidative stress, inflammation and endothelial dysfunction." (PMID 40552061, 2025). "Exogenous insulin antibody syndrome is a rare condition characterized by extreme insulin resistance caused by antibodies that neutralize the action of insulin." (PMID 40860576, 2025). "Elevated BCAA levels are linked to not only insulin resistance but also β-cell overload (as BCAAs can overstimulate insulin secretion acutely and impair it chronically)." (PMID 40871736, 2025).
Insulin resistance (continued). "The relationship between MSNA and the RDW was linked with the presentation of the metabolic syndrome and was associated with the level of adiposity, plasma insulin, the degree of insulin resistance, and the circulating level of hsCRP." (PMID 41017376, 2025). "The relationship between HI, steatosis, and insulin resistance is difficult to unpick, but it is thought that persistent HI and hepatic insulin resistance are both inciting causes and a result of MASLD, with a vicious cycle of pathology ensuing." (PMID 40476757, 2025). "Inflammatory mediators, such as TNF-α and IL-6, interfere with normal insulin function, ultimately leading to the onset of insulin resistance and an increased risk of developing prediabetes." (PMID 40997104, 2025). "Consistent with previous research, MTNR1B rs10830963 has been linked to impaired insulin secretion and altered glucose homeostasis, which can predispose individuals carrying the G allele to increased insulin resistance risk." (PMID 40428319, 2025). "T2D is a chronic metabolic disorder caused by a combination of insulin resistance and impaired insulin secretion." (PMID 40892247, 2025). "In both early and late pregnancy, the included molecules involved in the putative root cause (oxidative stress/inflammation) of insulin resistance and impaired insulin secretion by pancreatic β-cells." (PMID 41003859, 2025). "Nitric oxide deficiency contributes to insulin resistance primarily by impairing endothelial function, reducing insulin delivery to tissues, and disrupting insulin signaling pathways." (PMID 40564010, 2025). "Insulin resistance is associated with an impaired insulin signaling pathway, caused by defects in function of the insulin receptor." (PMID 39859258, 2025). "Elevated circulating levels of BCAAs have been linked to insulin resistance and metabolic aging and are frequently observed in obese and insulin-resistant individuals." (PMID 41007422, 2025). "Myonectin concentrations have been positively associated with measures of insulin resistance and negatively associated with insulin sensitivity, highlighting its role as a metabolic regulator linked to sarcopenic obesity." (PMID 40134450, 2025). "Low-grade inflammation in obese patients impacts negatively in insulin signaling pathways and causes insulin resistance, with IL-6 playing an important role in this process." (PMID 41141350, 2025). "Type 2 diabetes mellitus (T2DM) is a condition caused by insulin resistance, which is defined by the failing responses of cells in the liver, adipose tissue, pancreas, hypothalamus, and skeletal muscles to insulin." (PMID 40710317, 2025). "Myosteatosis is linked to insulin resistance and metabolic diseases including type 2 diabetes through several mechanisms including inflammatory cytokines, decreased insulin sensitivity index and glucose disposal rate and increased cholesterol." (PMID 40035123, 2025). "On one hand, DMPK gene mutations lead to RNA toxicity, causing abnormalities in insulin signaling pathways in skeletal muscle and adipose tissue, thus triggering insulin resistance." (PMID 41018201, 2025). "Recently, fat‐free mass indexed to height (fat‐free mass index; FFMI) has been shown to be positively associated with impaired insulin sensitivity or insulin resistance." (PMID 39895188, 2025). "Adiponectin is an adipokine that has anti-inflammatory and insulin-sensitizing properties, while resistin is another adipokine that antagonizes the action of insulin, causing glucose intolerance; increased resistin is associated with insulin resistance." (PMID 41441034, 2025). "Insulin resistance is common in older people with DM, where reduced insulin signalling pathways cause reduced protein synthesis and increased protein degradation, contributing to muscle mass loss." (PMID 40083990, 2025).
Insulin resistance (continued). "Concurrently, adiponectin expression, known for its anti-inflammatory properties and ability to enhance insulin sensitivity, was increased, whereas resistin expression, an adipokine linked to insulin resistance and inflammatory processes, was suppressed." (PMID 40733199, 2025). "Associations of baseline insulin and insulin resistance markers with cognitive end points (FINGER OGTT population with available data)." (PMID 40478656, 2025). "The rise in tissue lipid content largely contributes to impaired insulin action and is one of the main causative factors of insulin resistance." (PMID 40806520, 2025). "Insulin resistance has been linked with stroke via several mechanisms like interference with insulin signaling and sensitivity, amplification of chronic systemic inflammation, and accelerating foam cell generation causing atherosclerosis and advanced plaques." (PMID 40949739, 2025). "Based on this knowledge, this study aims to investigate the association between OSA and insulin clearance and hepatic insulin resistance in children and adolescents with obesity." (PMID 40365648, 2025). "This study demonstrates a significant association between shiftwork and elevated insulin resistance in professional drivers, using non-insulin-based surrogate measures (NIRS)." (PMID 39819581, 2025). "Type 1 diabetic patients who are obese develop worse glycemic control and need more insulin because obesity acts as a major risk factor for insulin resistance." (PMID 40225541, 2025). "Evidence links EDS to insulin resistance, independently of obesity, with studies showing associations between daytime sleepiness, fasting insulin levels, and HOMA-IR." (PMID 40806061, 2025). "It decreases oxidative stress by boosting endogenous antioxidant systems, moderates inflammatory responses linked to insulin resistance, and promotes insulin signaling through the activation of key cellular pathways, such as AMPK, and the modulation of IRS-1." (PMID 40563357, 2025). "In this longitudinal cohort of women with GDM, followed during pregnancy until 1-year postpartum, both CRF and HS during pregnancy were associated with improved hepatic insulin resistance, whole body insulin sensitivity and MetS-WC at 1-year postpartum." (PMID 41276872, 2025). "Effective insulin action is an important mechanism in regulating blood glucose levels and energy storage, with insulin resistance being a risk factor for T2D." (PMID 40283858, 2025). "The expansion of visceral adipose tissue stimulates an inflammatory response and produces cytokines that directly interfere with insulin signaling, leading to insulin resistance, which is a key risk factor for metabolic disorders." (PMID 39853044, 2025). "The T2DM pathogenesis is mainly insulin resistance (IR) and decreased insulin secretion caused by structural changes or a functional impairment of pancreatic β-cells." (PMID 40278571, 2025). "The fundamental cause of the development of NAFLD in poultry is linked to insulin resistance, a metabolic condition in which the body’s ability to respond to insulin is reduced." (PMID 40943380, 2025). "An abnormal glucose metabolism due to insulin resistance seems to be linked to aldosterone excess, which acts in several insulin‐target organs, such as the liver, skeletal muscle, and adipose tissue." (PMID 40079488, 2025). "Hyperglycemia caused by insulin resistance leads to Beta cell compensation that exacerbates insulin secretion resulting in Beta cell exhaustion and apoptosis." (PMID 40943107, 2025). "Future research should focus on elucidating the mechanisms underlying its effects on insulin signaling and insulin resistance." (PMID 40002361, 2025). "For example, Lactobacillus rhamnosus increases adiponectin levels in adipose tissue, leading to improved insulin sensitivity and a reduced risk of insulin resistance." (PMID 41154691, 2025).
Insulin resistance (continued). "Increases in body iron in SCD have been linked to increased oxidative stress and insulin resistance, which at the level of the liver, can interfere with insulin metabolism and negatively impact insulin signaling, hence leading to hyperglycemia." (PMID 40294908, 2025). "The elevation of HOMA-IR, a well-established indicator of insulin resistance, not only reflects diminished whole-body insulin sensitivity but also exhibits significant associations with oxidative stress, chronic inflammation, and metabolic toxicity." (PMID 41021555, 2025). "In T1D, the daily insulin dose normalized to body weight was positively associated with insulin resistance highlighting the role of chronic exogenous hyperinsulinemia." (PMID 39998445, 2025). "Aberrant methylation at specific CpG sites in pancreatic islets of T2DM patients has been linked to impaired insulin secretion and aggravated insulin resistance." (PMID 41471379, 2025). "It has been found that there is a causal relationship between obesity and insulin resistance and that changes in weight can either enhance or diminish insulin sensitivity." (PMID 40283443, 2025). "Puberty is associated with substantial changes in both insulin sensitivity and body composition, with physiological insulin resistance during mid-puberty and sex-specific patterns of fat and muscle mass accrual." (PMID 41374006, 2025). "Older individuals with insulin resistance experience accelerated muscle mass loss compared to non‐insulin‐resistant individuals due to age‐related reduction in available insulin‐responsive tissue, thereby promoting the insulin resistance." (PMID 39803274, 2025). "The predisposition of fatty tissue also intensifies inflammation and cytokine secretion, altering insulin signaling pathways and eventually causing insulin resistance in obesity." (PMID 39843936, 2025). "In type 2 diabetes, however, insulin resistance or deficient insulin secretion impairs GLUT4 translocation, leading to diminished glucose uptake and consequent hyperglycemia." (PMID 41471379, 2025). "Typical of manipulations that reduce insulin signaling and extend lifespan, Type I dInr genotypes retard growth, slow development, repress fecundity, and cause insulin-resistance." (PMID 40093182, 2025). "In women who already have insulin resistance prior to pregnancy (often associated with obesity), this additional insulin resistance can overwhelm the pancreas’s ability to produce insulin, leading to elevated blood sugar and GDM." (PMID 41302116, 2025). "The paths to β-cell demise and dysfunction are less well defined in type 2 than in type 1 diabetes, but deficient β-cell insulin secretion, frequently in the setting of insulin resistance, appears to be the common denominator." (PMID 41003147, 2025). "Type 2 diabetes is commonly associated with impaired insulin effectiveness at the cellular level, a condition known as insulin resistance." (PMID 40520537, 2025). "Humans with dominant-negative mutations in a single allele of PPAR-γ have partial lipodystrophy and insulin resistance, which is consistent with its crucial involvement in adipogenesis and insulin sensitization." (PMID 39762333, 2025). "This muscle loss further reduces the mass of insulin-responsivetissues, exacerbating insulin resistance." (PMID 39754576, 2025). "The failure of beta-cell function (BCF) and insulin resistance (IR, decreased insulin action), are two major risk factors for progression to T2D." (PMID 41561051, 2025). "Polymorphisms in the LF receptor gene (LRP1 rs4759277) have also been associated with fasting insulin levels and homeostatic modeling assessment of insulin resistance in patients with metabolic syndrome." (PMID 40313489, 2025). "Research has explored the use of newly developed incretin mimetics as standard therapy for insulin resistance in insulin-dependent tissues associated with PCOS." (PMID 41141001, 2025).
Insulin resistance (continued). "Exogenous insulin antibody syndrome (EIAS) is a rare cause of extreme insulin resistance (EIR) in patients exposed to exogenous insulin." (PMID 40860576, 2025). "In contrast to butyric acid, acetic acid has been associated with increased insulin resistance, enhanced insulin secretion, and elevated ghrelin secretion in response to glucose." (PMID 40343088, 2025). "Certain gut bacteria produce metabolites such as short-chain fatty acids (SCFAs) like butyrate and acetate, which improve insulin sensitivity and promote insulin secretion, partly by modulating the inflammatory pathways implicated in insulin resistance." (PMID 40806100, 2025). "Chronic activation of the IL-1β system is deleterious in pancreatic islets and insulin target tissues, disrupting insulin production (beta cell death) and causing insulin resistance." (PMID 40553147, 2025). "As a multifaceted chronic metabolic disease, the main causes of T2DM are inadequate insulin secretion and insulin resistance." (PMID 41300029, 2025). "The results of our study suggest that the development of DM after DP is not solely attributable to insulin deficiency but often involves insulin resistance or insufficient compensatory increase in peripheral insulin sensitivity." (PMID 40205383, 2025). "The present study elucidates the impaired insulin sensitivity associated with the progression of perimenopause and highlights the correlation between plasma exosomal miRNAs and the onset of insulin resistance." (PMID 39823117, 2025). "Conversely, individuals with DM are at increased risk of developing obesity due to insulin resistance, which raises hepatic glucose production and, consequently, insulin levels, further contributing to fat accumulation." (PMID 40070477, 2025). "T2DM is primarily attributed to insulin resistance and a relative deficiency in insulin secretion, influenced by a combination of genetic and environmental factors, as well as chronic inflammation." (PMID 40260282, 2025). "On the other hand, PTP1B is known to negatively regulate insulin and leptin signaling and has been implicated in the development of insulin resistance and obesity." (PMID 41012462, 2025). "Another advantage is the improvement of the body’s insulin sensitivity, thus reducing insulin resistance, the key underlying cause of type 2 diabetes." (PMID 40901288, 2025). "The high levels of insulin, chronic inflammation, and altered cellular energy usage associated with insulin resistance create an environment that can fuel the growth and spread of tumors." (PMID 41002547, 2025). "Chronic insulin resistance has also been implicated in the development of GDM as demonstrated by a 54% reduction in insulin stimulated glucose uptake compared to normal pregnancy." (PMID 40235646, 2025). "Long-term HFD-induced obesity can lead to severe insulin resistance in the body, thereby causing an increase in blood glucose and insulin levels." (PMID 40076847, 2025). "Insulin resistance, a hallmark of metabolic syndrome, occurs when cells become less responsive to insulin, leading to elevated blood sugar levels and increased insulin production by the pancreas." (PMID 40362807, 2025). "Insulin resistance resulting from chronic inflammation accompanying obesity leads to relative insulin deficiency, which forces the pancreatic islets to increase insulin secretion." (PMID 39940607, 2025). "Insulin resistance and impaired insulin secretion are the major underlying mechanisms of hyperglycemia in type 2 diabetes." (PMID 40002793, 2025). "HSP70 proteins modulate insulin signaling in response to various cellular stresses and are associated with the pathophysiology of insulin resistance and T2DM4,5,15." (PMID 41233317, 2025). "Estrogen deficiency disrupts hepatic insulin signaling by causing lipid-induced hepatic insulin resistance and impairing hepatocyte ERα signaling." (PMID 40522859, 2025).